BRCA1 (BRCA1 DNA repair associated)
Description:
E3 ubiquitin-protein ligase that specifically mediates the formation of 'Lys-6'-linked polyubiquitin chains and plays a central role in DNA repair by facilitating cellular responses to DNA damage. It is unclear whether it also mediates the formation of other types of polyubiquitin chains. The BRCA1-BARD1 heterodimer coordinates a diverse range of cellular pathways such as DNA damage repair, ubiquitination and transcriptional regulation to maintain genomic stability. Regulates centrosomal microtubule nucleation. Required for appropriate cell cycle arrests after ionizing irradiation in both the S-phase and the G2 phase of the cell cycle. Required for FANCD2 targeting to sites of DNA damage. Inhibits lipid synthesis by binding to inactive phosphorylated ACACA and preventing its dephosphorylation. Contributes to homologous recombination repair (HRR) via its direct interaction with PALB2, fine-tunes recombinational repair partly through its modulatory role in the PALB2-dependent loading of BRCA2-RAD51 repair machinery at DNA breaks. Component of the BRCA1-RBBP8 complex which regulates CHEK1 activation and controls cell cycle G2/M checkpoints on DNA damage via BRCA1-mediated ubiquitination of RBBP8. Acts as a transcriptional activator.
Synonyms: RNF53; BRCC1; PPP1R53; FANCS; BRCAI; BROVCA1; IRIS; PNCA4; PSCP
Tractability: Small molecule: it belongs to a druggable protein family. Antibody: its Gene Ontology location is reachable by antibodies, with high confidence. PROTAC: UniProt records ubiquitination sites on it; ubiquitination databases record sites on it; a small molecule that binds it is known.
Target class: Enzyme
Gene: Protein-coding gene on chromosome 17 (43,044,292 to 43,170,245, reverse strand). Ensembl gene ENSG00000012048.
Subcellular location: Nucleus; Chromosome; Cytoplasm; Cytoplasm (Isoform 3); Cytoplasm (Isoform 5)
Subcellular location (Human Protein Atlas): Nuclear bodies; Nucleoplasm
Pathways (Reactome):
DNA Repair: HDR through Homologous Recombination (HRR); HDR through Single Strand Annealing (SSA); Homologous DNA Pairing and Strand Exchange; Nonhomologous End-Joining (NHEJ); Presynaptic phase of homologous DNA pairing and strand exchange; Processing of DNA double-strand break ends; Recruitment and ATM-mediated phosphorylation of repair and signaling proteins at DNA double strand breaks; Resolution of D-loop Structures through Holliday Junction Intermediates; Resolution of D-loop Structures through Synthesis-Dependent Strand Annealing (SDSA)
Disease: Defective DNA double strand break response due to BARD1 loss of function; Defective DNA double strand break response due to BRCA1 loss of function; Defective HDR through Homologous Recombination Repair (HRR) due to PALB2 loss of BRCA1 binding function; Defective HDR through Homologous Recombination Repair (HRR) due to PALB2 loss of BRCA2/RAD51/RAD51C binding function; Defective homologous recombination repair (HRR) due to BRCA1 loss of function; Impaired BRCA2 binding to PALB2; Impaired BRCA2 binding to RAD51
Gene expression (Transcription): Transcriptional Regulation by E2F6
Metabolism of proteins: Metalloprotease DUBs; Neddylation; SUMOylation of DNA damage response and repair proteins
Reproduction: Meiotic recombination; Meiotic synapsis
Cell Cycle: G2/M DNA damage checkpoint
Cellular responses to stimuli: KEAP1-NFE2L2 pathway
Developmental Biology: Regulation of MITF-M-dependent genes involved in DNA replication, damage repair and senescence
Gene Ontology:
Molecular function: enzyme binding; identical protein binding; protein binding; RNA binding; RNA polymerase binding; transcription cis-regulatory region binding; transcription coactivator activity; ubiquitin protein ligase activity; ubiquitin protein ligase binding; ubiquitin-protein transferase activity; DNA binding; histone H2AK127 ubiquitin ligase activity; histone H2AK129 ubiquitin ligase activity; tubulin binding; ubiquitin-modified histone reader activity; zinc ion binding; damaged DNA binding; metal ion binding
Biological process: cellular response to indole-3-methanol; cellular response to ionizing radiation; cellular response to tumor necrosis factor; chromosome segregation; DNA damage tolerance; double-strand break repair; double-strand break repair via homologous recombination; intrinsic apoptotic signaling pathway in response to DNA damage; mitotic G2 DNA damage checkpoint signaling; negative regulation of cell growth; negative regulation of DNA-templated transcription; negative regulation of extrinsic apoptotic signaling pathway via death domain receptors; negative regulation of fatty acid biosynthetic process; negative regulation of gene expression via chromosomal CpG island methylation; negative regulation of intracellular estrogen receptor signaling pathway; negative regulation of reactive oxygen species metabolic process; positive regulation of angiogenesis; positive regulation of DNA repair; positive regulation of DNA-templated transcription; positive regulation of gene expression; positive regulation of transcription by RNA polymerase II; positive regulation of vascular endothelial growth factor production; protein autoubiquitination; protein K6-linked ubiquitination; protein ubiquitination; and 14 more
Cellular component: BRCA1-A complex; BRCA1-B complex; BRCA1-BARD1 complex; BRCA1-C complex; chromosome; cytoplasm; DNA repair complex; lateral element; nuclear body; nuclear ubiquitin ligase complex; nucleoplasm; nucleus; plasma membrane; protein-containing complex; ribonucleoprotein complex; gamma-tubulin ring complex; ubiquitin ligase complex; condensed chromosome; condensed nuclear chromosome; intracellular organelle lumen; XY body
Genetic constraint (gnomAD): Loss-of-function variants: 134 observed, 174.84 expected, observed/expected ratio (o/e) 0.77, 90% interval 0.67 to 0.88. The synonymous counts are far from expectation, so gnomAD's model fits this gene poorly and the ratio says little. Missense variants: 1,948 observed, 2,251.8 expected, observed/expected ratio (o/e) 0.87, 90% interval 0.83 to 0.9. Synonymous variants: 655 observed, 792.98 expected, observed/expected ratio (o/e) 0.83, 90% interval 0.77 to 0.88.
Gene-disease validity (ClinGen):
ClinGen rates the evidence that BRCA1 causes each of these diseases.
BRCA1-related cancer predisposition (autosomal dominant): Definitive. Hereditary cancer predisposition due to variation(s) in the BRCA1 gene.
Fanconi anemia, complementation group S (autosomal recessive): Definitive.
Cancer hallmarks: change of cellular energetics (promotes); angiogenesis (suppresses); genome instability and mutations (suppresses); invasion and metastasis (promotes); escaping programmed cell death (suppresses)
Homologues: Orthologues: chimpanzee BRCA1 (98% identical), macaque BRCA1 (93% identical), dog BRCA1 (74% identical), pig BRCA1 (73% identical), rabbit BRCA1 (69% identical), rat Brca1 (56% identical), mouse Brca1 (56% identical), tropical clawed frog brca1 (23% identical), Caenorhabditis elegans brc-1 (7% identical), Caenorhabditis elegans F42A6.5 (1% identical).
Diseases named in the same sentence as BRCA1 in open-access papers:
BRCA1 is named in the same sentence as 606 diseases in open-access papers, as found by Europe PMC text mining. Sharing a sentence is not in itself a finding about the gene and the disease. The quoted sentences say what the papers report.
breast cancer (6,251 papers, 1995 to 2026). A primary or metastatic malignant neoplasm involving the breast. "Our study investigated the performance of the TC risk model as a breast cancer risk predictor in patients with non‐BRCA1/2 PVs." (PMID 41568159, 2026). "Luminal progenitor cells (LPs) are the currently recognized cells of origin of BRCA1-deficient breast cancers." (PMID 41498327, 2026). "We investigated the contribution of non-coding variation to hereditary breast cancer by analyzing intronic variants and 5' upstream regions of BRCA1, BRCA2 and PALB2 in the BEACCON case-control study of over 11,000 participants." (PMID 41935071, 2026). "These drugs are used to treat many breast cancer subtypes, including HER2-positive, triple negative, hormone receptor-positive, and hereditary breast cancers driven by germline mutations in Breast Cancer genes 1 and 2 (BRCA1 and BRCA2)." (PMID 41536815, 2026). "The French LIBER Trial is studying the effect of letrozole, given at a dose of 2.5 mg daily for 5 years, in the primary prevention of breast cancer among 171 unaffected postmenopausal women aged 40 - 70 years with BRCA1 or BRCA2 mutation." (PMID 41488281, 2026). "BRCA1 is a critical tumor suppressor, mutations in which greatly increase risks for many tumors in carriers, most notably breast cancer." (PMID 41498327, 2026). "Poly(ADP-ribose) polymerase (PARP) inhibitors constitute the inaugural targeted therapy shown to enhance the prognosis of individuals with hereditary tumors, initially utilized in the management of patients with germline BRCA1/2-associated breast cancer." (PMID 41736752, 2026). "This review synthesises the genetic and epigenetic landscape of breast cancer susceptibility in African and diaspora cohorts, emphasising unique mutation spectra, elevated BRCA1 methylation frequencies and their prognostic/treatment implications." (PMID 41836332, 2026). "Our study reveals why BRCA1 deficiency is prone to result in tumorigenesis in LPs and elucidates the key role of replication stress and ELF3 during this process and suggests promising targets for BRCA1-associated breast cancers." (PMID 41498327, 2026). "Recent studies have investigated the ability of the TC to predict the risk of developing breast cancer in women with pathogenic variants (PVs) in genes, such as BRCA1/2." (PMID 41568159, 2026). "During cancer progression, BRCA1 mutant cancer cells gradually become reliant on high ELF3 expression to preserve a certain degree of genomic stability, making ELF3 a promising therapeutic target and biomarker in BRCA1-associated breast cancers." (PMID 41498327, 2026). "Triple-negative breast cancer (TNBC) is an aggressive and immunogenic breast cancer subtype frequently associated with BRCA1 alterations." (PMID 41865075, 2026). "We analysed our data according to the molecular subtype of breast cancer, tumour grade, lymph node invasion, and BRCA1 mutation status." (PMID 42122247, 2026). "Here, we investigate BRCA1 promoter methylation, its impact on gene expression, and its association with clinicopathological features in a cohort of African women with breast cancer." (PMID 42074525, 2026). "In this regard, the German approach differs from the ESMO guidelines, which advise starting intensified breast surveillance for women with pathogenic BRCA1/2 variants at age 30 or 5 years before the youngest age of breast cancer onset in the family." (PMID 41528496, 2026). "This study aimed to determine the frequency and spectrum of BRCA1/2 mutations among Kazakhstani breast cancer patients and to analyze their associations with clinicopathological features and survival outcomes." (PMID 41547905, 2026).
breast cancer (continued). "Talazoparib has shown anti‐tumour activity in patients with advanced breast cancer and in those carrying germline BRCA1 and BRCA2 (BRCA1/2) mutations." (PMID 41537447, 2026). "Approximately 70% of BRCA1-associated breast cancers are triple negative (TNBC; progesterone (PR), HER2, estrogen receptor (ER)-negative), which were reported to develop from ER/PR-negative luminal progenitor cells." (PMID 41896346, 2026). "Herein, it is shown that SYTL4 mRNA expression is significantly (p = 2.01 × 10-4) diminished in breast cancer bearing BRCA1 mutations, suggesting a mechanistic interplay between BRCA1-driven genomic instability and SYTL4-regulated signaling cascades." (PMID 42196512, 2026). "Olaparib is the first developed PARPi, which have been proved by the OlympiA trial to improve OS in germline BRCA1/2‐mutated early breast cancer (HR = 0.68)." (PMID 41510186, 2026). "LPs in the mammary gland are the currently recognized cells of origin of BRCA1-deficient breast cancers." (PMID 41498327, 2026). "While the TC is a widely used tool for breast cancer risk prediction, its limitations in predicting breast cancer risk in carriers of non‐BRCA1/2 PVs highlight the need for continued research into more accurate risk prediction models." (PMID 41568159, 2026). "Patients with BRCA1 or BRCA2-mutated carriers are advised to consider prophylactic bilateral mastectomy (PBM) which has been shown to reduce the incidence of breast cancer by approximately 90%." (PMID 41488281, 2026). "The 5-year cumulative risk (CR) of contralateral breast cancer (CBC) was 0.55 for BRCA1/2, 0.89 for ATM, and 0.80 for CHEK2 carriers." (PMID 41976331, 2026). "Here, using single-cell sequencing of human BRCA1 mutant breast cancers and RNA sequencing (RNA-seq) of BRCA1-deficient normal mammary cells, we reveal that replication stress is a feature of LPs and a driving factor during BRCA1-associated tumorigenesis." (PMID 41498327, 2026). "Olaparib is a PARP inhibitor, mainly used for the treatment of breast cancer patients with specific gene mutations (such as BRCA1/2)." (PMID 41123010, 2026). "For women at elevated risk for breast cancer due to a BRCA1 or BRCA2 pathogenic variant, RRM can significantly reduce risk while offering a prognosis and life expectancy comparable to that of surveillance, along with reduced fear." (PMID 41438882, 2026). "Investigating the traits of LPs is important for tumor prevention and treatment in BRCA1 mutation carriers and a wider range of patients with TNBCs and basal-like breast cancer." (PMID 41498327, 2026). "PARP1 inhibitors are FDA-approved for BRCA1/2-mutated breast cancer but show limited efficacy in wild-type cancers and face resistance issues." (PMID 41693691, 2026). "An analysis of TNBC as well as basal-like tumor data needs to be further confirmed in BRCA1-deficient breast cancer." (PMID 41498327, 2026). "Combining genetic and pharmacologic approaches to induce ssDNA accumulation alongside RPA exhaustion in vivo shows therapeutic efficacy in BRCA1-deficient breast cancer." (PMID 42049240, 2026). "(B) T-distributed statistical neighbor embedding (t-SNE) plots visualizing the replication stress scores and ELF3 expression levels in breast cancer and normal mammary tissue from a BRCA1-mutated triple-negative breast cancer patient." (PMID 41498327, 2026). "Men with a pathogenic BRCA1 variant exhibit a mildly elevated lifetime breast cancer risk of approximately 1%, while those with a pathogenic BRCA2 variant have a lifetime risk of around 8%." (PMID 41528496, 2026). "The TC risk model remains a useful tool for predicting breast cancer risk in certain patient populations, especially those with BRCA1/2 mutations, but its limitations must be considered when making clinical decisions." (PMID 41568159, 2026). "The currently recognized cells of origin of BRCA1-deficient breast cancers are the LPs in the mammary gland." (PMID 41498327, 2026).
breast cancer (continued). "Women with an elevated risk for breast cancer due to a BRCA1 or BRCA2 pathogenic variant can choose for surveillance or risk reducing mastectomy (RRM)." (PMID 41438882, 2026). "Our findings demonstrate that BRCA1 protein loss delineates a distinct aggressive tumor biology within high-risk breast cancers." (PMID 41751865, 2026). "Background/Objectives: Prophylactic mastectomy can significantly reduce the risk of breast cancer in patients carrying gene mutations such as BRCA1 and BRCA2." (PMID 41827488, 2026). "A large prospective study comparing early-onset breast cancer patients with BRCA1/BRCA2 germline mutations to those with sporadic cancer found no significant survival difference." (PMID 40841483, 2026). "The limitations of TC in predicting breast cancer risk in carriers of non‐BRCA1/2 PVs are significant, and this finding underscores the need for additional research into more accurate risk prediction models." (PMID 41568159, 2026). "Women harboring pathogenic variant (PV) in the BRCA1 or BRCA2 genes (= BRCA) have an elevated lifetime risk for breast cancer (BC)." (PMID 42126651, 2026). "RANK+ luminal progenitors in BRCA1-mutated breast tissue exhibit higher proliferative capacity and are considered precursors to basal-like breast cancers." (PMID 40243654, 2025). "Estimates show that before age 70, 55–65% of women with the BRCA1 mutation will develop breast cancer." (PMID 40283136, 2025). "The cGAS-STING pathway is activated in BRCA1-deficient breast cancer cells, leading to an upregulation of the expressions of CCL5 and CXCL10 and promotion of lymphocyte migration." (PMID 40830526, 2025). "Germline alterations in BRCA1 drive about 40%–45% of familial breast cancers but represent only 2%-3% of all breast cancer cases, since BRCA1 mutations are uncommon in sporadic tumors." (PMID 40904409, 2025). "DHC-1, a potent and selective PARP1 inhibitor, selectively inhibited PARP1 activity and showed efficacy in BRCA1-deficient breast cancer and BRCA2-deficient pancreatic cancer cell lines." (PMID 40521389, 2025). "For example, 19 genes exhibited comparable or even higher levels of essentiality than the well‐established breast cancer susceptibility gene BRCA1 (BRCA1CERESscore = −0.36)." (PMID 39950845, 2025). "Of the 143 patients, 24 (16.8%) had a PGV in a breast cancer susceptibility gene (BRCA1, n = 17; BRCA2, n = 5; PALB2, n = 1; CHEK2, n = 1)." (PMID 39964682, 2025). "Incorporation of computational chemistry has revolutionized the drug development paradigm for PARP1 inhibitors, allowing for unmatched accuracy and efficacy in designing therapies for breast cancer, particularly in BRCA1/2-mutated tumors." (PMID 41304924, 2025). "People with BRCA1/2 mutations are more at risk of breast cancer than people with BO are at risk of OAC." (PMID 39812114, 2025). "Patients treated for serous ovarian cancer with mutations in the BRCA1 or BRCA2 genes are at high risk of breast cancer and should be screened with mammography and breast MRI." (PMID 40406472, 2025). "The role of PARP1 in breast cancer is preeminent in BRCA1/2 mutations that impair homologous recombination repair (HRR) and make cells reliant on PARP1-catalyzed base excision repair (BER) for existence." (PMID 41304924, 2025). "Ovarian cancer data enabled an additional test for EBV involvement in breast cancer because, like breast cancer, BRCA1 or BRCA2 mutations can also predispose patients to ovarian cancer." (PMID 39885374, 2025). "The resulting data have revealed a differential cellular response for BRCA1-deficient and BRCA1-proficient breast cancer cells to the compound." (PMID 41155174, 2025). "Despite the complexity and heterogeneity of BRCA1-mutated breast cancer, only 18 lincRNAs associated with breast cancer have been annotated in the lincRNA Disease database for lincRNA-related disorders." (PMID 39997609, 2025).